MIF (macrophage migration inhibitory factor)
Diseases named in the same sentence as MIF in open-access papers (continued):
Sharing a sentence is not in itself a finding about the gene and the disease.
cancer (continued). "MIF is involved in 9 of the 10 hallmarks of cancer, and its inhibition by antibodies, nanobodies, or small synthetic molecules has shown promising results." (PMID 36672343, 2023). "Although some progress has been made in the current study on MIF regulation of immune responses and inflammatory responses in cancer, its biological functions related to oxidative stress need to be further explored." (PMID 37842089, 2023). "MIF is commonly overexpressed in many cancers and, when inhibited, anti-human MIF immunoglobulins coreceptors CD74 and CD44 are also downregulated leading to a decrease in cancer cell proliferation and migration." (PMID 37514190, 2023). "The complexity of MIF in cancer emphasizes the necessity of gaining a deeper understanding of its biological function." (PMID 37842089, 2023). "We demonstrated that Mif mRNA as well as intracellular and secreted MIF protein levels were increased in BM macrophages upon the efferocytosis of apoptotic cancer cells." (PMID 36496973, 2022). "Of note is that MIF has emerged as an inducer of cancer cell migration and invasion by up-regulating and activating matrix metalloproteases (MMPs), such as MMP2, MMP9 and MMP13, then contributed to degradation of ECM." (PMID 36703790, 2022). "We observed top-ranking ligand-receptor pairs of macrophage migration inhibitory factor (MIF) in cancer cells and (CD74+CD44) in macrophages." (PMID 36248860, 2022). "Macrophage migration inhibitory factor (MIF) secreted by CSCs inhibits anti-cancer immune responses via the CXCR2 pathway, increasing MDSC arginase-1 (ARG-1) expression and inhibiting CD8+T cell migration." (PMID 35269786, 2022). "Other downregulated proteins are involved in immune response, related to Myeloid-derived suppressor cells and M2 macrophages in cancer, MIF-mediated glucocorticoid regulation, and MIF-JAB signaling." (PMID 36614061, 2022). "MIF is a cytokine closely associated with cancer and functions as a promoter in inflammation, and inhibition of MIF can suppress cancer cell proliferation." (PMID 35733175, 2022). "In the research field of regulation of cancer cell invasion and metastasis, MIF showed similar effect or intersection with hypoxia, such as association with an increased expression of MMPs and PLAUR and macrophage recruitment." (PMID 36703790, 2022). "PEITC covalently modified MIF (macrophage Migration Inhibitory Factor), making it unsuitable for antibody binding during inflammatory processes, which made authors propose employment of PEITC as MIF inhibitor to tackle cancers and other inflammatory diseases." (PMID 35163897, 2022). "High MIF levels are found in almost all type of cancers exerting multifunctional effects contributing to cancer development and progression such as promoting migration and reducing apoptosis." (PMID 35628911, 2022). "Other downregulated proteins are associated with immune response, including those related to Myeloid-derived suppressor cells and M2 macrophages in cancer, MIF-mediated glucocorticoid regulation, and MIF-JAB signaling." (PMID 36614061, 2022). "Cancer cells in all three BC subtypes communicate with all other cell types through the MIF-TNFRSF14." (PMID 36077333, 2022). "Gremlin-1 was found to be positively correlated with MIF levels in pancreatic ductal adenocarcinoma, and inversely correlated with pro-tumorigenic M2 macrophage phenotype in the cancer microenvironment." (PMID 35203511, 2022). "Inhibition of MIF not only suppresses cancer cell proliferation, but also enhance the sensitivity of cancer cells to anticancer drugs, including EGFR-TKIs, and overcomes anticancer drug resistance." (PMID 35372081, 2022). "MIF is ubiquitously and constitutively expressed in almost all cells, including numerous human cancer types, and it is involved in numerous biological processes." (PMID 36703790, 2022). "In conclusion, TA-MSCs TA-MSCs-EVs and MIF effectively promote the occurrence and development of cancer through interactions with CSCs." (PMID 35842634, 2022).
cancer (continued). "There are already studies that have proven that higher human macrophage migration inhibitory factor (HuMIF) levels are present in several cancers, including PCa25." (PMID 36100630, 2022). "Under hypoxia, significant alterations in the mRNA expression of genes involved in invasion and metastasis were observed across different cancer types, including macrophage migration inhibitory factor (MIF)." (PMID 36703790, 2022). "MIF acts as an autocrine or paracrine cytokine, is upregulated in several types of cancer, and its expression correlates with disease malignancy and invasiveness." (PMID 36496973, 2022). "MIF is reported to be an upstream regulator of the mTOR signaling pathway, and the mTOR pathway is now considered a target for cancer therapy." (PMID 35280512, 2022). "Given the importance of MIF in malignant disease progression at hypoxia, in-depth studies of MIF directed therapeutics in cancer development are critical." (PMID 36703790, 2022). "Macrophage migration inhibitory factor (MIF) is a hypoxia-related pleiotropic cytokine that plays important roles in cancer." (PMID 36703790, 2022). "Previous studies demonstrated that MIF was able to induce macrophage M2 polarization, while knockdown of MIF expression facilitated macrophage M1 polarization in a various types of cancers." (PMID 36242053, 2022). "Among the receptor–ligand pairs with high interactions, cancer cells of the three BC subtypes communicate with all other cell types through the MIF-TNFRSF14." (PMID 36077333, 2022). "MIF is an upstream regulator of the host innate immune response and, when dysregulated, is a pivotal mediator of inflammatory diseases, autoimmunity, cancer, and cardiovascular diseases." (PMID 36094626, 2022). "In the current review, we discuss the role of MIF signaling pathways in inflammation and cancer and summarize the recent advances of the role of MIF in experimental and clinical exocrine pancreatic diseases." (PMID 33776775, 2021). "It has been reported that MIF inhibition can synergistically enhance the anti-cancer effects of common chemotherapy agents, such as temozolomide." (PMID 34516577, 2021). "Here, we showed that MIF is a novel 3’ flap nuclease that monitors replication errors in a real-time with its 3’ nuclease activity to promote cancer cell growth." (PMID 34012010, 2021). "Macrophage migration inhibitory factor (MIF) is a pleotropic inflammatory cytokine that is overexpressed in a number of cancer types including most types of human cancer." (PMID 34389619, 2021). "It has been reported that several cytokines, including GM-CSF, IL-6, IL-8, and macrophage migration inhibitory factor (MIF), are highly expressed by the cancer-associated MSCs." (PMID 34073849, 2021). "sEVs positive for integrins avß5 and macrophage migration-inhibitory factor (MIF) favor liver organotropism, a common site for metastasis associated with a poor prognosis in many types of cancer." (PMID 34503190, 2021). "These pathways provide mechanistic bases to explain the role of MIF in the action of pro-inflammatory effects and cancer progression." (PMID 33776775, 2021). "Intracellular macrophage migration inhibitory factor (MIF) usually becomes stable in human cancer cells." (PMID 34120619, 2021). "Previous studies have shown MIF as a potential molecular link between chronic inflammation and cancer." (PMID 34157052, 2021). "Median expression of MIF was similar in the benign (219.12 pg/ml) and the malignant tumors (262.59 pg/ml)." (PMID 34530759, 2021). "Pharmacological inhibition of MIF has been shown to hold great promise in treating inflammatory diseases and cancer, including small molecule MIF inhibitors targeting the tautomerase active site of MIF and antibodies that neutralize MIF." (PMID 33776775, 2021). "MIF is known to facilitate progression and metastasis for a wide spectrum of malignant neoplasms; its elevated concentrations in various solid tumors have been associated with adverse prognosis." (PMID 34068967, 2021).
cancer (continued). "MIF is widely expressed in various cell types, including cancer cells, neurons, monocytes, macrophages, vascular smooth muscle cells, and cardiomyocytes, and plays an important role in inflammation, immune response, and tumor growth." (PMID 34012010, 2021). "Altogether, rSmeg-hMIF-hIL-7 treatment increased neutralization of MIF in serum and suppressed the migration and invasion of cancer cells by neutralizing the biological activity of MIF." (PMID 34389619, 2021). "Previous research also showed that proinflammatory macrophages tend to turn into wound-healing macrophages with decreased MIF concentration in cancer patients." (PMID 34504539, 2021). "In the liver, MIF is not only produced by immune, endothelial cells, and cancer cells, but also by hepatocytes." (PMID 35087852, 2021). "MD13 suppresses the proliferation of A549 cells by reducing MIF protein levels and MIF‐related signaling, demonstrating the potential of PROTACs in cancer therapy." (PMID 34018657, 2021). "Macrophage migration inhibitory factor (MIF) represents a promising target for cancer immunotherapy." (PMID 34068967, 2021). "MIF has pleiotropic traits that play a main role in various inflammatory diseases as well as in cancer." (PMID 33356032, 2021). "Given that MIF tautomerase activity is positively correlated with MIF cancer-promoting signaling, an increase in anti-MIF IgG induced by rSmeg-hMIF-hIL-7 vaccination is likely to elicit anticancer effects by blocking MIF signaling." (PMID 34389619, 2021). "Increasing evidence showed that MIF was often overexpressed in cancer tissues and participated in the process of carcinogenesis." (PMID 35036405, 2021). "High expression level of MIF usually indicates advanced cancer phenotype and unsatisfactory prognosis in above tumors." (PMID 33314730, 2021). "Additional studies are required to explore if MIF is more vulnerable for growth of cancer cells than normal cells in future." (PMID 34012010, 2021). "MIF stabilization occurs via binding to Hsp9016, which offers therapeutic approaches to target cancer cells via Hsp90 inhibition." (PMID 33542244, 2021). "Altogether, development of these MIF degraders indicates a new strategy for treatment of cancers and also provides a new class of tools to study MIF." (PMID 34018657, 2021). "The aim of this review is to describe what is known about the structure and function of MIF with a particular focus on signaling pathways involved in inflammation and cancer." (PMID 33776775, 2021). "In this study, we found that PI3K/AKT/mTOR inhibitors upregulated MIF expression and secretion in several PTEN-deficient cancer cells, and activated STAT3 activity through JAK1, eventually limiting the effects of these inhibitors." (PMID 33431808, 2021). "MIF is one cytokine with T lymphocyte origin that presumably participates in an immune mechanism related to cancer microenvironment." (PMID 34157052, 2021). "We propose that MIF is a unique 3’ nuclease, excises flaps at the immediate 3’ end during DNA synthesis and favors cancer cells evading replication stress-induced threat for their growth." (PMID 34012010, 2021). "MIF is released by cancer cells during RT and, even though its role remains largely understood, the pro-oncogenic profile of MIF suggests its role in mitigating the beneficial effects of RT." (PMID 32854690, 2020). "In cancer, MIF predominantly signals through binding with the CD74 receptor, however, binding through the chemokine receptors CXCR2, CXCR4, and CD44 have also been shown." (PMID 32317702, 2020). "In recent years, several reports have shown that MIF is overexpressed in many cancers, including breast, colorectal, lung, prostate, and head and neck cancers." (PMID 32943608, 2020). "MIF is highly over-expressed in many types of malignant tumors and its level of upregulation has been correlated with the aggressiveness of the cancers." (PMID 32318567, 2020).
cancer (continued). "Initial studies by ourselves and others have primarily evaluated the role of MIF in the pathogenesis of immunoinflammatory and autoimmune diseases and cancer." (PMID 32344747, 2020). "Several clinical trials have been undertaken and/or are currently underway investigating prospective MIF or MIF receptor inhibition in human cancers." (PMID 33324425, 2020). "Cancer biology studies have shown that CD74 bound to MIF initiates survival and cell proliferation through the phosphoinositide-3-kinase (PI3K)/protein kinase B (Akt) and extracellular signal-regulated kinase (ERK) signaling pathways." (PMID 32004754, 2020). "Studies have also shown high expression of MIF in pancreatic cancer Importantly, the expression of MIF is directly and positively correlated with the aggressiveness of the cancer phenotype." (PMID 32317702, 2020). "MIF have been suggested to be the “key” that links inflammation with cancer development and progression." (PMID 32317702, 2020). "Macrophage migration inhibitory factor (MIF) is a pleiotropic cytokine that plays a key role in several diseases, including cancer." (PMID 32155795, 2020). "In H. pylori-positive group, the MIF level was significantly elevated in cancer subgroup than in control or dysplasia subgroups." (PMID 30742638, 2019). "H. pylori-positive cancer group showed significantly higher MIF levels than H. pylori-positive control group, which remained constant throughout the follow-up period (P < 0.05)." (PMID 30742638, 2019). "Macrophage migration inhibitory factor (MIF) is an evolutionarily conserved, multifunctional cytokine, which has been implicated in the pathogenesis of many cancers and inflammatory diseases." (PMID 31440740, 2019). "Macrophage migration inhibitory factor (MIF) is an inflammatory cytokine involved in the carcinogenesis of many cancer types." (PMID 31013837, 2019). "Studies have shown that pharmacological inhibition of Hsp90 activity destabilizes MIF in many different cancer cells." (PMID 31013837, 2019). "In the recent past, studies have demonstrated the presence of a high level of MIF in different cancer patients." (PMID 31664114, 2019). "The H. pylori-positive cancer group showed significantly higher levels of MIF than control and dysplasia subgroups of patients, throughout the follow-up period." (PMID 30742638, 2019). "Macrophage migration inhibitory factor (MIF) is a pleiotropic cytokine that increasingly is being studied in cancers and inflammatory diseases." (PMID 31664114, 2019). "On the front of cancer cells, both H460R and A549R cells showed a significant increase in the mRNA level of Src, IL-4, IL-10 and MIF as compared to their parental counterparts." (PMID 31036057, 2019). "A four-biomarker panel (CA125, osteopontin (OPN), macrophage inhibitory factor (MIF), and anti-IL-8 autoantibodies) detected 82% of early stage cancers compared to 65% with CA125 alone." (PMID 31035430, 2019). "MIF is involved in several pathological conditions, such as infections and cancer, explaining why therapeutic approaches aimed at inhibiting MIF activities use ISO-1 as a potential tool." (PMID 31068920, 2019). "During the last few years, several small molecule inhibitors of MIF have been shown to exert chemotherapeutic effects in rodent models of cancer." (PMID 31635049, 2019). "TAMs produce macrophage migration inhibitory factor (MIF), which has been associated with EMT in many types of cancer including HNSCC." (PMID 30927923, 2019). "It has been noted that the effects of MIF in cancer mainly occur through its binding to the CD74 receptor, even if other receptors, such as the chemokine receptor CXCR4, or the CD44 receptor, have also been reported to be involved in MIF signaling." (PMID 31013837, 2019). "In most of the studies trying to understand the role of MIF in the progression of different cancers, MIF expression was knocked down in overexpressing cancer cells." (PMID 31664114, 2019).
cancer (continued). "Based on the outcomes of this method, MCDC exerts cytotoxic effects against many cancer cell lines by inhibiting the downstream pathways of MIF." (PMID 30765775, 2019). "The major objective of the current study was to check how MaMIF affects different cell types (immune or cancer) and compare it with the already reported properties of human MIF." (PMID 31664114, 2019). "When study population was divided into cancer and non-cancer groups regardless of H. pylori status, the cancer group showed significantly higher MIF level than the non-cancer counterpart (9.37±1.57 vs. 3.66±0.49, mean ± standard error, P = 0.001)." (PMID 30742638, 2019). "When HSP90 inhibitors are used in cancer cell lines, this leads to augmented degradation of MIF, that is accompanied by acquisition of favorable anticancer activities." (PMID 29707160, 2018). "Our work proposes a novel mechanism through which MIF controls cancer growth and progression through manipulation of the host immune system." (PMID 29864117, 2018). "In summary, these studies highlight the importance of controlling MIF expression in preventing atrial electrical remodeling in patients with cancer." (PMID 30386232, 2018). "Delivery of siRNA to migration inhibitory factor (MIF) in glucan NPs reduced both released and intracellular MIF in TAMs and in cancer cells." (PMID 29670528, 2018). "The ACK activities of MIF contribute to its key role in inflammatory and cardiovascular diseases and cancer." (PMID 29581527, 2018). "We thus examined the phenotypic characteristic cancers with significant loss of COX-2 activity and significant gain of MIF activity (as observed in COX-2−/− cells) from the IntOGen database." (PMID 29247872, 2017). "The selective inhibitor of COX-2, NS-398 not only augmented the expression of MIF but induced differentiation of cancer cells." (PMID 29247872, 2017). "For the roles of MIF in supporting cancer, there exists possibility that it can be a therapeutic target for cancer." (PMID 27788497, 2017). "Conversely, inhibition of MIF/CD74 signalling axis elevated ROS rendering cancer cells vulnerable to oxidative stress-induced cell death." (PMID 28114961, 2017). "Macrophage migration inhibitory factor (MIF) is expressed at high levels in various inflammatory diseases and cancer." (PMID 27619729, 2017). "Macrophage migration inhibitory factor (MIF) is over-expressed and secreted in various cancer cells in particular in response to hypoxia." (PMID 29113309, 2017). "Among them, MIF is notable, as it was validated as a target gene of mir-451 in different types of cancers, including gastric cancer, colon cancer, nasopharyngeal carcinoma and osteosarcoma." (PMID 28704499, 2017). "In several tumoral cells (breast, colon, prostate, lung...), MIF signaling in cancer is well described to be triggered by its receptor CD74." (PMID 26883190, 2016). "Here, we have discovered that ionizing radiation (IR) and other DNA damaging stresses can induce robust MIF secretion in several cancer cell lines." (PMID 26741693, 2016). "Appreciation of elevated MIF levels has led to targeting strategies and biomarker studies that hold promise to improve cancer therapies." (PMID 26741693, 2016). "The specific expression of oxMIF in cancerous tissue allows for targeted inhibition of disease-related functions of MIF in cancer." (PMID 27636991, 2016). "The pleiotropic nature of MIF signaling implies a broad role for MIF in promoting cancer, and in cancer recurrence." (PMID 26741693, 2016). "We utilized two previously established ELISA methods to quantify oxMIF and total MIF, which reflects the sum of oxMIF and redMIF, in plasma samples of cancer patients and healthy controls." (PMID 27636991, 2016). "The role of MIF in tumorigenesis has been characterized in other cancers however its function in GBC is yet to be established." (PMID 26530123, 2015).